Y_RNA (Y RNA )
Gene: Miscellaneous RNA gene on chromosome 12 (114,657,949 to 114,658,062, reverse strand). Ensembl gene ENSG00000199220.
Homologues: Orthologues: chimpanzee Y_RNA (98% identical), macaque Y_RNA (95% identical). Paralogues in human: RNY1 (86% identical), Y_RNA (84% identical), Y_RNA (83% identical), Y_RNA (82% identical), Y_RNA (81% identical), Y_RNA (80% identical), RNY1P8 (79% identical), Y_RNA (79% identical), RNY1P11 (78% identical), Y_RNA (78% identical), RNY1P7 (77% identical), Y_RNA (77% identical), and 95 more.